PHTF2 (putative homeodomain transcription factor 2)
Synonyms: DKFZp434D166
Tractability: Antibody: UniProt predicts a signal peptide or a membrane-spanning region. PROTAC: ubiquitination databases record sites on it.
Gene: Protein-coding gene on chromosome 7 (77,798,761 to 77,957,503, forward strand). Ensembl gene ENSG00000006576.
Subcellular location: Membrane
Subcellular location (Human Protein Atlas): Nucleoplasm; Cytosol
Gene Ontology:
Cellular component: endoplasmic reticulum; membrane
Genetic constraint (gnomAD): Loss-of-function variants: 10 observed, 15.22 expected, observed/expected ratio (o/e) 0.66, 90% interval 0.4 to 1.12. The upper end of that interval is the gene's LOEUF score, 1.12, which puts it in group 4 of 6, group 1 being the genes least tolerant of losing a copy. Missense variants: 198 observed, 257.91 expected, observed/expected ratio (o/e) 0.77, 90% interval 0.68 to 0.86. Synonymous variants: 74 observed, 87.59 expected, observed/expected ratio (o/e) 0.84, 90% interval 0.7 to 1.02.
Homologues: Orthologues: chimpanzee PHTF2 (99% identical), macaque PHTF2 (99% identical), rabbit PHTF2 (97% identical), dog PHTF2 (97% identical), pig PHTF2 (96% identical), guinea pig PHTF2 (94% identical), mouse Phtf2 (93% identical), rat Phtf2 (93% identical), tropical clawed frog phtf2 (84% identical), Drosophila melanogaster phtf (37% identical), zebrafish phtf2 (25% identical). Paralogues in human: PHTF1 (55% identical).
Diseases named in the same sentence as PHTF2 in open-access papers:
PHTF2 is named in the same sentence as 6 diseases in open-access papers, as found by Europe PMC text mining. Sharing a sentence is not in itself a finding about the gene and the disease. The quoted sentences say what the papers report.
breast carcinoma (1 paper, 2024). "Our study showed that low expression of HCG9 and high expression of PHTF2 resulted in the high survival rate of breast cancer patients." (PMID 38978021, 2024).
gastric cancer (1 paper, 2023). A primary or metastatic malignant neoplasm involving the stomach. "It was reported that fatty acid metabolism mediated by PHTF2 can greatly impact the tumorigenic potential of gastric cancer cells both in vivo and vitro studies." (PMID 38069522, 2023).
tumor (3 papers, 2020 to 2026). "The expression levels of PHTF2, MFAP2, INHBA, TSPAN9, and CCL26 (p < 0.05) displayed tumor stage-dependent alterations." (PMID 34456964, 2021). "Moreover, significant differences were found in the expressions of INHBA, CCL26, MFAP2, TSPAN9, and PHTF2 in tumor stage based on TCGA-ESCA, suggesting their prognostic value in ESCC tumor development." (PMID 34456964, 2021).
hematological cancers (1 paper, 2023). "Although its essential paralog PHTF1 has been overexpressed in T‐ ALL cell lines to regulate cell proliferation and apoptosis, the association of PHTF2 with other hematological cancers has not been reported." (PMID 38069522, 2023).
PHTF2 also shares sentences with these, for which no sentence is quoted: cancer (2 papers); thyroid cancer (1).